BRAF (B-Raf proto-oncogene, serine/threonine kinase)
Diseases named in the same sentence as BRAF in open-access papers (continued):
Sharing a sentence is not in itself a finding about the gene and the disease.
adenoma (continued). "The BRAF mutation frequency of polypoid and flat adenomas was similar to the reported literature." (PMID 22848674, 2012). "However and since BRAF mutation seems to associate with SLC5A8 methylation in this group of adenomas, it would be unlikely." (PMID 21687703, 2011). "Either BRAF or KRAS mutation was observed in 82.4% of serrated adenomas (P < 0.001)." (PMID 21457162, 2011). "In addition to the 186 cancer samples analysed, 16 unselected adenomas were also tested for mutation in BRAF and K-ras." (PMID 20233436, 2010). "Moreover, the locational distribution of adenomas with this epigenetic alteration was also similar to that of adenomas with K-ras/BRAF mutations, although the frequency of the epigenetic change as a whole was lower than that of the genetic changes." (PMID 17923875, 2007). "Consequently, serrated adenomas were likely to have both K-ras/BRAF mutations and RASSF2 methylation (5 out of 8, 63%), despite relatively dispersed locational distribution." (PMID 17923875, 2007). "There was a locational imbalance among K-ras/BRAF mutations or RASSF2 methylation in adenomas." (PMID 17923875, 2007). "Of the 120 adenomas, 49 (41%) exhibited K-ras/BRAF mutations." (PMID 17923875, 2007). "Moreover, our results indicated that K-ras/BRAF mutations in adenomas were significantly less frequent in the distal colon than in either the proximal colon or the rectum." (PMID 17923875, 2007). "Overall, KRAS mutation occurred in 26.5% of adenomas while BRAF mutation was detected in only 4.8%." (PMID 16879389, 2006). "KRAS mutation occurred in 26.5% and BRAF mutation in 4.8% of adenomas (all types) (P < 0.0001)." (PMID 16879389, 2006). "Similarly, the BRAF mutation frequency was only 2% in adenomas." (PMID 31690257, 2019). "For example, the additional driver mutation could be the mutation activating the KRAS/BRAF pathway in a small colorectal adenoma, associated with the transformation from small to large adenoma, or the mutation that transforms benign adenoma into infiltrating carcinoma." (PMID 23396615, 2013). "While the invasive and metastatic process is studied in WNT-driven adenomas, the BRAF-driven serrated cancer invasion process is still relatively understudied." (PMID 38136364, 2023). "Most biomarkers for the outcome of adenocarcinoma used in histology are related to the adenoma-carcinoma pathway and show mutations in oncogenes such as KRAS, NRAS, BRAF, APC, and DDF." (PMID 38187473, 2023). "Instead, mutations in KRAS, or more commonly BRAF, activate the RAS–RAF–MEK–ERK–MAPK axis as these are the earliest mutations observed in sessile serrated adenomas and its precursor hyperplastic polyps." (PMID 35975243, 2022). "For example, Mutations in BRAF (P = 0.004), a gene highly associated with a variation on the usual CRC adenoma-carcinoma progression theme and the altered DNA-methylation phenotype known as CIMP, showed a tendency to be clonal." (PMID 35962343, 2022). "Additional mutations, such as the human gene that encodes a protein called B-Raf (BRAF) protein pathway, resulted in the growth of a small adenoma with clinically significant size (>1 cm)." (PMID 35454852, 2022). "A sessile serrated adenoma is highlighted by BRAF V600E point mutation, CIMP, and MLH1 methylation compared to classic adenomas." (PMID 36341436, 2022). "In previous studies, somatic mutations in KRAS, BRAF, and PIK3CA have been found in CRC or adenomas from other germline gene mutation carriers." (PMID 34549727, 2021).
adenoma (continued). "Two high-risk cases were distinguished by the presence of BRAF p.V600E and PIK3CA p.E545K mutations, whereas one adenoma of the low-risk cases showed NRAS p.G12D." (PMID 34372923, 2021). "In contrast to conventional adenomas, BRAF V600E is the most highly prevalent driver for SSA/P neoplasia." (PMID 34298598, 2021). "With the recognition of the importance of USP8 mutations, another two mutated genes in the mitogen-activated protein kinase (MAPK) pathway, USP48 and BRAF, have also been detected in corticotropin-secreting adenomas." (PMID 33574795, 2020). "In this group, 58 polyps were analyzed (41 tubular adenomas with low-grade dysplasia, 15 HP and 2 sessile serrated adenoma/polyps (SSA/p) and 13.8% were KRAS-mutated (n = 8/58) while 20.7% were BRAF-mutated (n = 12/58)." (PMID 32517177, 2020). "This prospective study aims to evaluate the performance of RAS and BRAF-mutated ctDNA in detecting CRC and advanced adenomas (AA)." (PMID 32517177, 2020). "In this study, the BRAF-V600E mutation was identified in only 0.7% (3/401) of all CRC cases and 2% (2/98) of adenoma cases." (PMID 31690257, 2019). "Colon adenomas and serrated adenomas have the same mutation frequencies, but the genes involved differed substantially, the most mutated genes in conventional adenomas being APC and the most mutated genes in serrated adenomas being BRAF." (PMID 29652830, 2018). "There is a continuum of tumourigenesis from a BRAF mutant sessile serrated adenoma that methylates MLH1 at the point of dysplasia which then can rapidly progress to a BRAF mutant/MSI cancer." (PMID 30598662, 2018). "The early gene mutations responsible for initial adenoma mutation are represented by APC mutations, and for adenoma enlargement by KRAS and BRAF mutations." (PMID 29652830, 2018). "DNA from 76 formalin-fixed, paraffin-embedded (FFPE) adenoma specimens, mostly low-grade and small lesions, was tested to identify mutations in KRAS and BRAF oncogenes." (PMID 30166531, 2018). "Here, we performed further exome sequencing and identified recurrently-mutated genes including BRAF and USP48 in USP8 wild-type corticotroph adenomas." (PMID 30093687, 2018). "With regards to gender, this is the first study to demonstrate a strong male predominance in metanephric adenomas that are BRAF wild-type." (PMID 28903326, 2017). "K-RAS and BRAF showed a consistent trend of increased expression from the hyperproliferative to adenoma and subsequent carcinoma groups." (PMID 27880935, 2017). "One study suggests combining conventional adenomas and LAMN into a single diagnostic category in part because of their high rates of KRAS and low rates of BRAF mutation; however, their capacity for peritoneal dissemination differs." (PMID 28591173, 2017). "Generally, it has been seen that conventional adenomas follow the traditional pathway of developing cancer with CIN, CIMP-negative, MSS, BRAF wild type and KRAS mutated." (PMID 27902488, 2017). "SAC morphology was observed in 38% of MACs, and was associated with proximal location (P=0.001), BRAF mutation (P=0.042), CIMP-positive status (P=0.023), and contiguous traditional serrated adenoma (P=0.019)." (PMID 28422723, 2017). "We previously showed that the TET1 gene is preferentially methylated in CIMP-positive and BRAF mutant CRCs and adenomas, which suggests TET1 is one of the genes affected by CIMP-related hypermethylation." (PMID 27977763, 2016). "Cancer (214 BRAF mutant, 122 BRAF wild type) and polyp (59 serrated polyps, 40 conventional adenomas) cohorts were analysed for PRDM5 promoter methylation using MethyLight technology." (PMID 25613750, 2015).
adenoma (continued). "It has been shown that BRAF mutations are frequent in sporadic CRC with MSI (32–74 %) and in serrated polyps (up to 90 % in sessile serrated adenomas)." (PMID 26220423, 2015). "These precursor lesions that harbor BRAF mutation, microsatellite instability and CIMP phenotype have a distinct morphology and are termed serrated adenomas." (PMID 25005754, 2014). "Mixed effects models revealed that mutations in APC, BRAF and KRAS occur at the transition from normal to adenoma stages whilst the hypermethylation of the Wnt antagonists continued to accumulate during the transitions from adenoma to carcinoma stages." (PMID 25432628, 2014). "AMACR is essential for the completion of the β-oxidation pathway and has recently been shown to upregulated in colorectal cancer and adenoma; 4) BRAF, MLH1 and β-catenin as additional markers involved in the serrated adenocarcinoma carcinogenesis." (PMID 24152881, 2013). "Subsequently, we compared the BRAF/KRAS mutational and the microsatellite stability status of the RCTs with the matched tubular adenomas (TAs) and normal mucosa." (PMID 23425390, 2013). "Of note, all of the adenomas analyzed exhibited APC inactivating mutations (exon 15) in combination with KRAS (G12D, G13D, Q61H) or BRAF (V600E) activating mutations." (PMID 23919615, 2013). "CIN develops in conventional adenomas which are BRAF wild type and progress towards malignancy via the ‘traditional pathway’." (PMID 23110075, 2012). "Two of the four nucleotide positions known to carry BRAF mutations in CRC were successfully analyzed, including c.1799T>A (p.V600E), (with 88.64% the most frequently mutated BRAF position in adenomas)." (PMID 22848674, 2012). "Our results suggested that K-ras/BRAF mutations and RASSF2 methylation can cooperate and work synergistically in adenomas." (PMID 17923875, 2007). "The cited study also had five additional patients of epithelial-predominant tissue without BRAF V600E mutations or metanephric adenoma-like regions." (PMID 39148862, 2024). "Moreover, in human organoid cultures of premalignant colorectal lesions, TGFβ induces cell death in conventional adenoma-derived organoids but strongly induces EMT in organoids harboring mutant BRAF as a model for early serrated lesions." (PMID 38731846, 2024). "The oncogene BRAF, commonly associated with SSAs, was found in four patients (including three TVAs and one TA) and was exclusively comutated with KRAS, corroborating previous findings on conventional adenomas." (PMID 39554798, 2024). "We next determined whether Fn infection was associated with BRAF mutation, KRAS mutations or MLH1 hypermethylation in adenomas/polyps." (PMID 37772997, 2023). "Compared with carcinoma, Fn infection in adenoma/polyps seems random, not selective to BRAF- or KRAS-mutated cases and is characterized by poor bacterial-enabling growth as indicated by a lower number of Fn copies." (PMID 37772997, 2023). "BRAF and KRAS genes were mutually exclusive mutated, except for one advanced adenoma." (PMID 35761395, 2022). "A following case series, however, found such a mutation in a single case out of 94 examined adenomas, while other authors have not found any BRAF mutations, even with whole exome sequencing." (PMID 35743266, 2022).
adenoma (continued). "Cross-sectional reports have also substantially manifested that over-representation of malignancy hallmarks in SPs including BRAF mutation, MLH1 methylation, MUC5AC demethylation, and CIMP proposes possibly higher risks of CRC compared to conventional adenomas." (PMID 35402217, 2022). "An alternative hypothesis, supporting an age at diagnosis that is similar to conventional pathway cancers and the morphology of our murine adenomas, is that polyps are initiated by APC, acquiring a BRAF mutation." (PMID 32384699, 2020). "Importantly, if we exclude the cases of adenomas coexisting with the PTC, all BRAF non p.V600E mutations were identified only in tissue adjacent to PTCs harboring the BRAF p.V600E mutation." (PMID 32059434, 2020). "Most BRAF non p.V600E exon 15 mutations were identified in the non neoplastic tissue adjacent to the PTC, and remarkably—after exclusion of the adenomas—all BRAF non p.V600E mutations were identified only in tissue adjacent to PTCs harboring the BRAF p.V600E mutation." (PMID 32059434, 2020). "This suggests that BRAF and APC mutations are mutually exclusive in conventional adenomas." (PMID 32384699, 2020). "For example, the frequency of BRAF mutation was found to be 67% among 200 traditional serrated adenomas, but no BRAF mutations were identified in 50 control tubulovillous adenomas." (PMID 31690257, 2019). "Recently, ACF were identified in the proximal colons of about 40% of individuals undergoing high-resolution chromoendoscopy and more frequently in patients with synchronous proximal adenomas; somatic mutations of APC, BRAF, KRAS, NRAS and ERBB2 were detected in 37% of proximal ACF." (PMID 29652830, 2018). "A recent study reported a mouse model of colon serrated adenomas based on the development of conditional BRAF V637E (the equivalent in the mouse of the human V600E mutation): these mice developed serrated polyps, characterized by hyperplasia that, with time, progressed to dysplasia." (PMID 29652830, 2018). "The incidence of serrated lesions in the population is 5% to 8% (compared with 30% to 40% for adenomas) 6,7; moreover, with the exception of HPs, SPs are considered precursors of CRC due to BRAF mutation and CpG island methylator phenotype (CIMP) with or without microsatellite instability (MSI)." (PMID 30304298, 2018). "Immunohistochemical analysis further proved that BRAF-mutated, but not wild-type corticotroph adenomas were positive for phosphorylation of Nur77, c-jun, and c-fos." (PMID 30093687, 2018). "High-MSI CRCs may develop from a subset of hyperplastic polyps (which often have BRAF mutations and CIMP-H), and microsatellite-stable cancers with BRAF mutations may develop from adenomas with BRAF mutations." (PMID 30071442, 2018). "Among advanced lesions, we observed that no advanced adenoma carried a BRAF mutation, but 45% of advanced serrated lesions harboured this mutation." (PMID 28953955, 2017). "The molecular mechanisms underlying the adenoma-carcinoma sequence has been extensively studied and involves a cumulative acquisition of mutations in tumor suppressor genes, such as APC, and oncogenes such as KRAS and BRAF, leading to genomic instability." (PMID 26910894, 2016). "Aggressive serrated BRAF-mutated/CIMP-positive/MSS tumors will probably necessitate more aggressive treatment and, potentially, different treatment agents than CRC exhibiting high levels of MSI or CRC resulting from the traditional adenoma–carcinoma sequence." (PMID 26337942, 2015). "In adenomas, BRAF mutations were specific to serrated adenomas, as none of the non-serrated adenomas showed a BRAF mutation (P = 0.058)." (PMID 21457162, 2011). "Because of the low number of adenomas available for analysis and the lack serrated adenomas in this sample set (none were included), the observation that none of the 16 adenomas tested harboured BRAF mutation was expected." (PMID 20233436, 2010).
adenoma (continued). "Patients who had at least one adenoma carrying either K-ras/BRAF mutations or RASSF2 methylation or both were significantly older than those who had adenoma(s) without these alterations (70 vs 62 years, P=0.01)." (PMID 17923875, 2007). "In 18 patients harbouring plural adenomas, 2 patients each carried two adenomas with K-ras/BRAF mutations, while no patients had two or more adenomas with RASSF2 methylation." (PMID 17923875, 2007). "Then, to identify factors for the concomitance of K-ras/BRAF mutations and RASSF2 methylation in adenomas, univariate and multivariate logistic regression analyses were performed with parameters including gender, age, location, morphology, size, and histological diagnosis." (PMID 17923875, 2007). "Alternatively, however, a specific synergistic correlation between BRAF mutation and RASSF2 methylation may function in Ras signalling disorders during the progression of serrated adenomas." (PMID 17923875, 2007). "Some adenomas in the proximal colon carried neither K-ras/BRAF mutations nor RASSF2 methylation, while there were few cancers without these alterations." (PMID 17923875, 2007). "CRC with the BRAF and KRAS mutations, derived from the serrated or conventional adenoma-to-carcinoma pathways (discussed further in detail later), are also represented by distinct epigenetic subtypes that may represent basic differences in transcriptional programs involved in these cancers." (PMID 35975243, 2022). "Despite the well characterized “adenoma-carcinoma sequence”, approximately 10–15% of sporadic CRCs originate from serrated polyps which have been identified as an alternative key pathway that harbors, e.g., the CpG island methylator phenotype (CIMP), and its close relation to BRAF mutations." (PMID 35741223, 2022). "However, numerous studies have indicated that mutation of BRAF is almost never identified in such APC mutated adenomas, even when they develop advanced histological features." (PMID 32384699, 2020). "However, the majority of BRAF non p.V600E mutations were identified not in the adenomas—coexisting with the PTC as an incidental finding in the thyroidectomy specimen—but in the non neoplastic tissue adjacent to the PTC." (PMID 32059434, 2020). "From findings associating the key genetic events of BRAF mutation and hypermethylation events being present in the earliest form of serrated precursor lesions and not in conventional-type adenomas, a continuum of serrated tumourigenesis from early serrated ACF to MVHP then to SSA was proposed." (PMID 30598662, 2018). "The main finding of this study was that patients with at least one polyp that harboured a KRAS mutation were at higher risk of developing advanced polyps, specifically, advanced adenomas, compared to patients with polyps that harboured BRAF mutations or no mutation." (PMID 28953955, 2017). "Moreover, a subset (15%) of metanephric adenomas does not have BRAF mutation, prompting again careful use as a diagnostic tool." (PMID 28903326, 2017). "In part because BRAF mutations are common in SSAs/SSPs and HPPs and not in conventional adenomas, it has been argued that CRCs arising from serrated precursor lesions may harbor BRAF mutations more often than CRCs arising from the conventional adenoma pathway." (PMID 28072391, 2017). "Mutant BRAF may, in part, drive the histologic progression of adenomas toward serrated histology." (PMID 26910894, 2016). "No BRAF mutations were found in all analyzed adenomas and normal adjacent mucosa." (PMID 23425390, 2013). "Thus, characteristics of adenomas in each patient were not always the same regarding K-ras/BRAF mutations or RASSF2 methylation." (PMID 17923875, 2007). "Adenomas with RASSF2 methylation were more likely to carry K-ras/BRAF mutations than those without RASSF2 methylation (73 vs 30%, P<0.01), suggesting that these genetic and epigenetic alterations are mutually correlated and may work synergistically." (PMID 17923875, 2007).